RNU6-1012P (RNA, U6 small nuclear 1012, pseudogene)
Gene: Small nuclear RNA gene on chromosome 12 (73,679,188 to 73,679,296, reverse strand). Ensembl gene ENSG00000252415.
Homologues: Orthologues: chimpanzee U6 (99% identical), rat U6 (71% identical), mouse Gm26011 (65% identical). Paralogues in human: RNU6-1099P (74% identical), RNU6-16P (72% identical), RNU6-869P (72% identical), RNU6-1075P (72% identical), RNU6-19P (72% identical), RNU6-301P (72% identical), RNU6-536P (72% identical), RNU6-1060P (71% identical), RNU6-1181P (71% identical), RNU6-12P (71% identical), RNU6-13P (71% identical), RNU6-29P (71% identical), and 1285 more.